HSPH1 (heat shock protein family H (Hsp110) member 1)
Description:
Acts as a nucleotide-exchange factor (NEF) for chaperone proteins HSPA1A and HSPA1B, promoting the release of ADP from HSPA1A/B thereby triggering client/substrate protein release. Prevents the aggregation of denatured proteins in cells under severe stress, on which the ATP levels decrease markedly. Inhibits HSPA8/HSC70 ATPase and chaperone activities (By similarity).
Synonyms: HSP105; KIAA0201; HSP105B; HSP105A; NY-CO-25
Tractability: Small molecule: a structure with a bound ligand is known. Antibody: its Gene Ontology location is reachable by antibodies, with high confidence. PROTAC: ubiquitination databases record sites on it; its protein half-life has been measured.
Target class: Other cytosolic protein
Gene: Protein-coding gene on chromosome 13 (31,134,876 to 31,162,388, reverse strand). Ensembl gene ENSG00000120694.
Subcellular location: Cytoplasm
Subcellular location (Human Protein Atlas): Cytosol; Nucleoplasm
Pathways (Reactome):
Cellular responses to stimuli: Attenuation phase; HSF1 activation; HSF1-dependent transactivation; Regulation of HSF1-mediated heat shock response
Vesicle-mediated transport: Scavenging by Class F Receptors
Gene Ontology:
Molecular function: adenyl-nucleotide exchange factor activity; protein binding; alpha-tubulin binding; ATP binding; ATP hydrolysis activity
Biological process: positive regulation of MHC class I biosynthetic process; positive regulation of NK T cell activation; protein folding; response to unfolded protein
Cellular component: cytoplasm; cytosol; extracellular exosome; nucleoplasm; protein-containing complex; endocytic vesicle lumen; extracellular region; microtubule; nucleus
Genetic constraint (gnomAD): Loss-of-function variants: 23 observed, 74.93 expected, observed/expected ratio (o/e) 0.31, 90% interval 0.22 to 0.44. The upper end of that interval is the gene's LOEUF score, 0.44, which puts it in group 1 of 6, group 1 being the genes least tolerant of losing a copy. Missense variants: 704 observed, 844.34 expected, observed/expected ratio (o/e) 0.83, 90% interval 0.78 to 0.89. Synonymous variants: 320 observed, 290.06 expected, observed/expected ratio (o/e) 1.1, 90% interval 1.01 to 1.21.
Homologues: Orthologues: chimpanzee HSPH1 (100% identical), macaque HSPH1 (98% identical), dog HSPH1 (96% identical), rabbit HSPH1 (96% identical), guinea pig Hsph1 (95% identical), mouse Hsph1 (93% identical), rat Hsph1 (92% identical), pig HSPH1 (92% identical), tropical clawed frog hsph1 (73% identical), zebrafish hsph1 (54% identical), Drosophila melanogaster Hsp110 (42% identical), Caenorhabditis elegans hsp-110 (40% identical), and 3 more. Paralogues in human: HSPA4 (63% identical), HSPA4L (58% identical), HYOU1 (27% identical), HSPA1L (25% identical), HSPA8 (24% identical), HSPA1A (24% identical), HSPA1B (24% identical), HSPA6 (24% identical), HSPA2 (24% identical), HSPA5 (22% identical), HSPA9 (20% identical), HSPA14 (15% identical), and 1 more.
Diseases named in the same sentence as HSPH1 in open-access papers:
HSPH1 is named in the same sentence as 94 diseases in open-access papers, as found by Europe PMC text mining. Sharing a sentence is not in itself a finding about the gene and the disease. The quoted sentences say what the papers report.
colorectal cancer (26 papers, 2005 to 2025). A primary or metastatic malignant neoplasm that affects the colon or rectum. "In addition, HSPH1 mutation enhanced chemosensitivity to drugs, such as oxaliplatin and 5-fluorouracil, and improved prognosis in colorectal cancers with microsatellite instability." (PMID 34712697, 2021). "In colorectal cancer, HSPH1 promoted the phosphorylation and activation of STAT3 through a direct interaction with STAT3." (PMID 32091104, 2020). "And HSPH1 was highly expressed in different tumors, such as colorectal cancer, B-cell lymphoma, melanoma and esophageal squamous cell carcinoma, while NAA25 knockdown could upregulate IFIT2 and NDRG1 expression and downregulate HSPH1 expression." (PMID 35096568, 2021).
melanoma (18 papers, 2011 to 2024). A malignant, usually aggressive tumor composed of atypical, neoplastic melanocytes. "HSPH1 is overexpressed in various human cancers, including non‐Hodgkin's lymphoma, melanoma, and colon cancer." (PMID 38444279, 2024). "HSPH1 has been reported to be over-expressed in melanoma and colon cancer patients." (PMID 32523426, 2020).
breast cancer (11 papers, 2016 to 2026). A primary or metastatic malignant neoplasm involving the breast. "The protein heat shock 105 kDa/110 kDa protein 1 (HSPH1), another HSP, can be induced by several kinds of environmental stress and is associated with mammary tumor tissues." (PMID 29843597, 2018). "Notably, HspH1 overexpression is a prognostic biomarker that overall correlates with poor survival in breast cancer patients." (PMID 33525518, 2021).
colon cancer (11 papers, 2004 to 2025). "HSPH1 is associated with the occurrence of colon cancer, as it is highly expressed in intestinal epithelial cells and plays a functional role in regulating mucosal homeostasis." (PMID 38444279, 2024). "While evidence of HSPH1 associating with colon cancer abounds, current research on RPS21 in colon cancer, regarding its expression levels, functions, and potential therapeutic targets, is not yet comprehensive." (PMID 39872660, 2024). "In colon tissue, we noted regulatory effects of estrogen on colon cancer-related risk genes such as RPS21 and HSPH1." (PMID 39872660, 2024). "Research has shown that HSPH1 plays a functional role in colon cancer cell proliferation through the IL‐6‐STAT3 pathway activation in vitro and in vivo." (PMID 38444279, 2024). "In colon cancer, HSPH1 plays a role in the Wnt/β‐catenin pathway by inhibiting β‐catenin hyperphosphorylation and degradation." (PMID 38444279, 2024).
B-cell lymphoma (8 papers, 2019 to 2024). "Inhibition of HSPH1 downregulates the expression of Bcl-6 and c-Myc and hampers the growth of human aggressive B cell non-Hodgkin lymphoma." (PMID 33042807, 2020). "HSPH1 is known to bind c-Myc proteins in aggressive B-cell lymphomas, modulating c-Myc expression by preventing its degradation via its chaperone activity." (PMID 31296583, 2019).
lymphoma (6 papers, 2016 to 2024). A malignant (clonal) proliferation of B- lymphocytes or T- lymphocytes which involves the lymph nodes, bone marrow and/or extranodal sites. "The identification of HSPH1 as a c-Myc mRNA interactor in K562 cells suggests a similar relationship and may indicate the utility to therapeutically target this heat-shock protein in c-Myc driven lymphomas." (PMID 31296583, 2019).
Alzheimer disease (5 papers, 2011 to 2023). A progressive, neurodegenerative disease characterized by loss of function and death of nerve cells in several areas of the brain leading to loss of cognitive function such as memory and language. "We will demonstrate the usage of the five nested information levels in CanIsoNet via the example of the transcript HSPH1-002, which we found as a dMDT in over 20% of Alzheimer’s disease samples." (PMID 37123454, 2023). "For example, a switching event in the MDT of the HSPH1 gene is among the top 10 most frequent dMDT in Alzheimer’s disease." (PMID 37123454, 2023). "CRYAB and HSPH1 are both chaperone proteins that prevent aggregation of mutant proteins and defects in CRYAB have been associated with Huntington’s disease and Alzheimer’s disease, where its levels decrease in age-dependent manner." (PMID 31260448, 2019). "Novel candidates are associated with neurodegenerative disorders including Alzheimer's disease (VSNL1), prion disease (SCRG1, HSPH1, HSPA5 and CTR9) and age-related degeneration (GAS6 and GNG11)." (PMID 21569303, 2011).
esophageal cancer (5 papers, 2014 to 2024). A primary or metastatic malignant neoplasm involving the esophagus. "High HSPH1 expression has been found to promote chemoresistance in oral and oesophageal cancers." (PMID 38444279, 2024).
lung adenocarcinoma (5 papers, 2016 to 2025). A carcinoma that arises from the lung and is characterized by the presence of malignant glandular epithelial cells. "It has been suggested that the analysis of HSPH1 expression levels may help in predicting the effectiveness of chemotherapeutic approaches acting on the EGFR-TKI pathway in advanced lung adenocarcinoma." (PMID 36298586, 2022).
B cell diffuse large B cell lymphoma (3 papers, 2021 to 2024). "HSPH1 stimulates NF-κB signaling through MyD88 stabilization in activated B cell diffuse large B cell lymphoma." (PMID 38932372, 2024).
Burkitt lymphoma (2 papers, 2023 to 2024). A rare form of malignant mature B-cell non-Hodgkin lymphoma. "Previous studies have shown that HSP110, also called HSP105 or HSPH1, is essential for the survival of Burkitt’s lymphoma (BL), mainly because its inhibition reduces the expression of c-Myc, a transcription factor acknowledged as an HSP110 client and key in driving BL survival." (PMID 38067355, 2023).
head and neck cancer (2 papers, 2020 to 2021). A primary or metastatic malignant neoplasm affecting the head and neck. "Previous analysis illustrated that frequent mutations of HSPH1, HSPD1, HSPA4 and HSP90AA1 were detected in head and neck cancer in head and neck squamous carcinoma." (PMID 34712697, 2021).
head and neck squamous cell carcinoma (2 papers, 2023 to 2025). A squamous cell carcinoma that arises from any of the following anatomic sites: lip and oral cavity, nasal cavity, paranasal sinuses, pharynx, larynx, and salivary glands. "The results demonstrated that HSPH1 was significantly elevated in a range of tumours, including breast, ovarian, head and neck squamous cell carcinoma, and renal clear cell carcinoma." (PMID 40395325, 2025). "Indeed, HSP90AA1 is highly coexpressed with HSPH1 during head and neck squamous cell carcinoma (HNSCC), which means that these factors could be either prognostic biomarkers or potential clinical targets." (PMID 36766730, 2023).
hepatocellular carcinoma (2 papers, 2021 to 2025). A malignant tumor that arises from hepatocytes. "For example, high expression of HSPH1 in hepatocellular carcinoma is associated with tumour metastasis." (PMID 40395325, 2025).
lung carcinoma (2 papers, 2021 to 2025). "Subsequently, the expression levels of HSPH1 in Lung cancer cell lines, human NSCLC tissues and normal tissues were determined using various experiments." (PMID 40395325, 2025). "Notably, a study in lung cancer found that silencing HSPH1 significantly increased the anti-tumour effect of gefitinib in non-small cell lung cancer, suggesting that HSPH1 may be a potential biomarker for the diagnosis, targeted therapy and prognostic evaluation of a variety of human tumours." (PMID 40395325, 2025). "To further validate the positive results of the bioinformatics analysis, we detected the expression of HSPH1 in human NSCLC tissues and lung cancer cell lines." (PMID 40395325, 2025).
non-small cell lung carcinoma (2 papers, 2021 to 2025). A group of at least three distinct histological types of lung cancer, including non-small cell squamous cell carcinoma, adenocarcinoma, and large cell carcinoma. "HSPH1 may therefore serve as a pivotal prognostic marker for NSCLC, particularly in the context of non-small cell lung cancer progression." (PMID 40395325, 2025).
oral cancer (2 papers, 2017 to 2020). "Both Hsp90 (HSP90AA1; heat shock protein 90 kDa α (cytosolic), class A member 1) and Hsp110 (HSPH1; heat shock 105 kDa/110 kDa protein 1) were markedly reduced in miR-27a mimic-transfected oral cancer HSC-4 cells." (PMID 28708091, 2017).
atherosclerosis (1 paper, 2022). A disease characterized by the build-up of fatty material and calcium deposition in the arterial wall resulting in partial or complete occlusion of the arterial lumen. "Heat shock protein family H member 1 (HSPH1), as a molecular chaperone, was associated with lipid droplets and was upregulated in atherosclerosis." (PMID 36712272, 2022).
brain trauma (1 paper, 2022). "The promoter region of the HSPH1/HSP110 gene is bound by HSF246, and the HSP110 protein is involved in brain integrity in models of brain trauma, neuropsychiatric, and neurodegenerative disorders, as well as in important neurodevelopmental processes." (PMID 36385105, 2022).
Cerebral ischemia (1 paper, 2025). Restriction of arterial blood supply to the brain associated with insufficient oxygenation to support the metabolic requirements of the tissue. "NAP-induced down-regulation of various ER stress genes in males, including those encoding the pro-neuroinflammatory Nkd2, Hsph1 (Hsp110/105) and Fam107a (DRR1), which were shown to exacerbate cerebral ischemia, and Mertk, the mediator of alpha-synuclein fibril uptake." (PMID 39715923, 2025).
dilated cardiomyopathy (1 paper, 2022). Cardiomyopathy which is characterized by dilation and contractile dysfunction of the left and right ventricles. "Furthermore, Hsph1 combined with Vegfa was positively correlated with dilated cardiomyopathy (DCM)-induced heart failure (HF) and had high accuracy in the diagnosis of DCM-induced HF (AUC = 0.898, P = 0.000)." (PMID 36712272, 2022).
esophageal adenocarcinoma (1 paper, 2022). A malignant tumor with glandular differentiation arising predominantly from Barrett mucosa in the lower third of the esophagus. "Similarly, the increased expression of HSPH1, IDH3G, NUDT7 and PDHA1 was associated with shorter OS in the subgroup of patients suffering from esophageal adenocarcinoma (EAD)." (PMID 36298586, 2022).
Fanconi anaemia (1 paper, 2025).
leishmaniasis (1 paper, 2024). Infectious disease that is transmitted through the bite of hematophagous female phlebotomine sand flies. "Through PPI network analysis, hub genes such as Lcn2, Ltf, Mpo, Dnaja1, Hspa1a, Hspa1b and Hsph1 were screened out and might play important roles in the process of undernutrition promoting leishmaniasis." (PMID 38185681, 2024).
neuroblastoma (1 paper, 2023). Neuroblastoma (NB) is the most common solid, extracranial childhood tumor. "We calculated the pairwise correlation coefficients for HSPA6 and HSPH1 co-expression in neuroblastoma SH-SY5Y and differentiated SH-SY5Y cells." (PMID 36979108, 2023). "DNAJB1 overexpresses 7- and 5-fold for neuroblastoma SH-SY5Y [SH] and differentiated SH-SY5Y [SH(D)], respectively; BAG3 at 11- and 6-fold; and HSPH1 at 2.7- and 3.2-fold." (PMID 36979108, 2023).
uterine corpus endometrial carcinoma (1 paper, 2021). A endometrial carcinoma (disease) that involves the body of uterus. "For example, the expression of HSPA8 and HSPH1 could be increased and related to good prognosis of patients with their mutations in uterine corpus endometrial carcinoma; HSPA12A mutation in lung adenocarcinoma could down-regulate its expression and lead to poor prognosis." (PMID 34712697, 2021). "Notably, the mutation of six HSPs, including HSPA4L, TRAP1, HSPH1, HSP90AA1, HSPA8 and HSPA9, was associated with their protein expression in uterine corpus endometrial carcinoma (p < 0.05)." (PMID 34712697, 2021).
tumor (55 papers, 2009 to 2026). "The results indicated that, in the univariate Cox regression analysis, the expression of HSPH1, age, and tumour stage were identified as risk factors (P < 0.05)." (PMID 40395325, 2025). "In addition to its protective function, HSPH1 is also associated with tumour cell proliferation, differentiation, invasion and metastasis." (PMID 40395325, 2025). "Furthermore, HSPH1 has the capacity to activate signaling pathways and transcription factors that are linked to the proliferation of tumor cells." (PMID 41312360, 2025). "In order to gain insight into the correlation between HSPH1 gene expression and tumour diseases, we analysed the expression profiles of 33 tumours in the TCGA database." (PMID 40395325, 2025). "A recent study demonstrated that YTHDF1 is highly expressed in response to N-methyl-N-nitrosourea (MNU) stimulation, subsequently promoting the translation of the HSPH1 protein in an M6A-dependent manner, which facilitates tumor cell proliferation." (PMID 41312360, 2025). "HSPH1 can activate proliferation‐related signalling pathways and transcription factors in tumour cells." (PMID 38444279, 2024). "Generally, heat shock protein family genes (HSPD1, HSPA1B, HSP90AB1, and HSPH1) enhance tumor growth and invasion through complex intracellular signaling networks." (PMID 37533434, 2023). "Further, PAK4 regulates the ratio of M1/M2 tumor-associated macrophages (TAM) through HSPH1, and PAK1 regulates chemotaxis and crawling along the tumor microvessel through LIMK1/Cofilin in neutrophils." (PMID 36230657, 2022). "We also observed a significant correlation between the expression of HSPH1 and tumor stage in HNSC patients." (PMID 32523426, 2020). "HSPH1 secreted from colorectal carcinoma cells induced macrophage differentiation favoring a pro-tumor, anti-inflammatory profile." (PMID 28468249, 2017). "In addition, we found genes associated with tumor progression were downregulated; among these were heat shock proteins (HSP), such as HSPH1, HSPD1, LYAR and EPHA2." (PMID 38992681, 2024). "Both RPS21 and HSPH1 have been reported to be involved in tumor progression." (PMID 39872660, 2024). "The multi-omics analysis of bioinformatics revealed that PAK4 is rich in the “T cell receptor signaling pathway” regulates macrophage polarization through heat shock protein 105 kDa (HSPH1), and significantly impacts neoantigen production and tumor immune regulation." (PMID 35800076, 2022). "Consistent with the findings in tumor, HSPH1 was required for STAT3 phosphorylation in LPS-AMs." (PMID 32091104, 2020). "In addition, HSPH1 was negatively correlated with inhibition of NK cell activity and regulatory T cells (Tregs), suggesting that it may promote tumour immune escape by modulating the immunosuppressive microenvironment." (PMID 40395325, 2025). "Second, in this study, HSPH1 was found to be significantly highly expressed in NSCLC tissues, and its expression level was strongly correlated with tumour stage (T, N, M) and clinical stage." (PMID 40395325, 2025). "Demonstrated as potent enhancers of tumor and cellular survival in cellular stress, the upregulation of the epichaperome genes HSP90AA1, HSPH1, and HSPA8 promotes the equilibrium of radio- and chemoresistance seen in tumor and indirect cell dormancy." (PMID 38994941, 2024). "Whereas JUN, HSPH1, HSPA8, HSPA6, HSP90AB1, and EGR1 were found to be the DEGs in both Tumor vs. normal and tumor vs. metastasis group." (PMID 37335089, 2023). "In contrast, for the primary tumor cell line SW480, only 3 genes (HIP1, HSPH1, HTT) showed significant oscillations." (PMID 32295075, 2020). "We also analyzed HSPH1, HSPD1, SERPINH1, HSPA4, and HSP90AA1 expression as a function of the HNSC tumor stage." (PMID 32523426, 2020). "In summary, our results indicate that HSPH1, HSPD1, SERPINH1, HSPA4, and HSP90AA1 are significantly upregulated in HNSC patients and their upregulation is negatively correlated with HNSC tumor stage." (PMID 32523426, 2020).